KIZ (kizuna centrosomal protein)
Description:
Centrosomal protein required for establishing a robust mitotic centrosome architecture that can endure the forces that converge on the centrosomes during spindle formation. Required for stabilizing the expanded pericentriolar material around the centriole.
Synonyms: C20orf19; NCRNA00153; PLK1S1; HT013; Kizuna; RP69
Tractability: PROTAC: ubiquitination databases record sites on it.
Gene: Protein-coding gene on chromosome 20 (21,125,975 to 21,246,622, forward strand). Ensembl gene ENSG00000088970.
Subcellular location: Cytoplasm, cytoskeleton, microtubule organizing center, centrosome; Cytoplasm, cytoskeleton, cilium basal body
Gene Ontology:
Molecular function: protein binding; protein kinase binding
Biological process: spindle organization
Cellular component: centrosome; cytoplasm
Genetic constraint (gnomAD): Loss-of-function variants: 30 observed, 33.15 expected, observed/expected ratio (o/e) 0.9, 90% interval 0.68 to 1.23. The upper end of that interval is the gene's LOEUF score, 1.23, which puts it in group 5 of 6, group 1 being the genes least tolerant of losing a copy. Missense variants: 447 observed, 436.89 expected, observed/expected ratio (o/e) 1.02, 90% interval 0.95 to 1.11. Synonymous variants: 149 observed, 150.05 expected, observed/expected ratio (o/e) 0.99, 90% interval 0.87 to 1.14.
Gene-disease validity (ClinGen):
ClinGen rates the evidence that KIZ causes each of these diseases.
KIZ-related retinopathy (autosomal recessive): Definitive. Any retinopathy caused by variants in the KIZ gene.
Homologues: Orthologues: chimpanzee KIZ (99% identical), macaque KIZ (93% identical), dog KIZ (75% identical), rabbit KIZ (74% identical), mouse Kiz (68% identical), rat Kiz (68% identical), guinea pig KIZ (61% identical), pig KIZ (55% identical), tropical clawed frog kiz (35% identical), zebrafish kiz (22% identical).
Diseases named in the same sentence as KIZ in open-access papers:
KIZ is named in the same sentence as 17 diseases in open-access papers, as found by Europe PMC text mining. Sharing a sentence is not in itself a finding about the gene and the disease. The quoted sentences say what the papers report.
autism (3 papers, 2021 to 2025). Persistent deficits in social interaction and communication and interaction as well as a markedly restricted repertoire of activity and interest as well as repetitive patterns of behavior. "KIZ has been identified as significantly associated with autism in previous GWAS, TWAS, gene based analysis, and methylation-based studies, and the involvement of cell cycle regulation in autism susceptibility has also been implicated in previous research." (PMID 40373085, 2025). "It is worth noting that this study also found evidence of SNPs associated with both autism and DNA methylation that were annotated to KIZ and XRN2, two genes that we also found to be significantly associated with ASD." (PMID 37790478, 2023). "KIZ has been identified as significantly associated with autism in previous GWAS, TWAS, gene-based analysis, and methylation-based studies, and the involvement of cell cycle regulation in autism susceptibility which has also been implicated in previous research." (PMID 37790478, 2023).
retinal disease (2 papers, 2016 to 2024). "There were discernible differences in the PCA1 scores between 2 groups; patients with mutations in DHDDS and FAM161A exhibited lower PCA1 scores, indicative of a more severe retinal disease compared to patients with mutations in KIZ and MAK." (PMID 38927740, 2024).
Rod-cone dystrophy (2 papers, 2017). An inherited retinal disease subtype in which the rod photoreceptors appear to be more severely affected than the cone photoreceptors. "The homozygous nonsense mutation in KIZ (c.226C>T; p.Arg76*) was previously reported in two families with recessive rod-cone dystrophy: one family of North African Sephardic Jewish origin and the other of Spanish ancestry." (PMID 28837078, 2017). "We identified herein additional patients with rod-cone dystrophy (RCD) displaying mutations in KIZ, encoding the ciliary centrosomal protein kizuna and performed functional characterization of the respective protein in human fibroblasts and of its mouse ortholog PLK1S1 in the retina." (PMID 29057815, 2017).
cataract (1 paper, 2022). Partial or complete opacity of the crystalline lens of one or both eyes that decreases visual acuity and eventually results in blindness. "Particularly, mutations in three of them, AGBL4, DYNC2H1, and KIZ, cause retinal pathologies in humans, while a NID1 mutation was found to be the cause of the development of recessive cataracts in Romagnola cattle." (PMID 36669004, 2022).
schizophrenia (1 paper, 2022). A major psychotic disorder characterized by abnormalities in the perception or expression of reality. "Interestingly, other variants were found in hmsLRI-E connected to genes that had not been previously associated with schizophrenia (KIZ, CDKAP2, EPN2, MAPK7, B9D1)." (PMID 35887306, 2022).
neurological disorders (1 paper, 2025). "KIZ has also been found to be a potentially shared genetic loci between ASD and attention-deficit hyperactivity disorder (ADHD), providing support for its involvement in neurological disorders." (PMID 40373085, 2025).
retinopathies (1 paper, 2017). "This variability may explain the restricted retinal phenotype found in our RCD patients carrying KIZ mutations and other cases of isolated retinopathies linked to mutations on other ciliary proteins." (PMID 29057815, 2017).
KIZ also shares sentences with these, for which no sentence is quoted: cancer (1 paper); ciliopathies (1); colitis (1); glaucoma (1); mastitis (1); neurodevelopmental disorder (1); nyctalopia (1); progressive external ophthalmoplegia (1); renal cell carcinoma (1); retinitis pigmentosa (1).